UCP2 (uncoupling protein 2)
Diseases named in the same sentence as UCP2 in open-access papers (continued):
Sharing a sentence is not in itself a finding about the gene and the disease.
skin cancer (3 papers, 2012 to 2022). "Therefore, in an attempt to understand how UCP2 regulates cellular energy metabolism during skin carcinogenesis, we performed a protein microarray analysis using the skin tumor tissues obtained from wild-type and UCP2 knockout mice at the end of a skin carcinogenesis study." (PMID 29221144, 2017). "During our previous skin carcinogenesis study using UCP2 KO mice, phosphorylated PFKFB2 was found to be upregulated in skin tumor tissues of the wild-type mice but not the UCP2 knockout mice, suggesting that UCP2 may positively regulate PFKFB2 expression." (PMID 29221144, 2017). "In this study, we identified that PFKFB2 was upregulated in skin tumor tissues of the wild-type mice but not in the UCP2 knockout mice, suggesting that PFKFB2 expression may be positively regulated by UCP2." (PMID 29221144, 2017).
subarachnoid hemorrhage (3 papers, 2020 to 2024). A serious neurological disorder characterized by intracranial hemorrhage into the subarachnoid space. "The anti-apoptosis function of Irisin is partially guaranteed by mitochondrial uncoupling protein 2 (UCP-2) protein during brain injury, resulting in elevated mitochondrial biogenesis in subarachnoid hemorrhage." (PMID 37047523, 2023). "Activated PKA improved the expression levels of UCP2 and suppressed OS and neuronal apoptosis after subarachnoid hemorrhage in rats." (PMID 33101590, 2020).
adenoma (2 papers, 2015 to 2017). A neoplasm arising from the epithelium. "UCP2 is an uncoupling protein isoform that has been shown to be overexpressed in adenomas and CRC in a stage-dependent manner." (PMID 28423551, 2017). "In this set, expression of UCP2 was significantly decreased in carcinomas compared to adenomas." (PMID 26148070, 2015). "The comparison of adenomas without 13q gain to carcinomas with 13q gain, showed for both UCP2 and COPS2 significantly decreased expression in carcinomas with 13q gain." (PMID 26148070, 2015). "Both UCP2 and COPS2 were significantly decreased in adenomas and carcinomas with a 13q gain compared to those without." (PMID 26148070, 2015).
Alzheimer disease (2 papers, 2017 to 2023). A progressive, neurodegenerative disease characterized by loss of function and death of nerve cells in several areas of the brain leading to loss of cognitive function such as memory and language. "In Alzheimer's disease, oleanolic acid regulates UCP2 expression via STC-1 to attenuate oxidative stress and β-amyloid levels in N2a/APP695swe cells." (PMID 38127054, 2023).
aneurysm (2 papers, 2021 to 2023). Bulging or ballooning in an area of an artery secondary to arterial wall weakening. "In Ang II-induced aortic aneurysm, UCP2 counteracts Ang II-stimulated ROS production, evident by increased incidence of aneurysms and oxidative stress in UCP2-/- mice." (PMID 38188249, 2023). "Moreover, aneurysm samples showed upregulation of genes involved in mitochondrial uncoupling and glycolytic rewiring (UCP2, HIF1A, and MYC)." (PMID 33709773, 2021).
aortic aneurysm (2 papers, 2017 to 2023). A ruptured aneurysm located in the wall of the proximal portion of the descending aorta proceeding from the arch of the aorta. "We first determined if UCP-2 expression showed any differences in the aortic aneurysm." (PMID 28683125, 2017). "Besides, UCP-2 has been well-established as an apoptosis suppressor in different cell systems while vascular smooth muscle cells apoptosis has been documented in the aortic aneurysms and dissections." (PMID 28683125, 2017). "UCP-2 knockout up-regulated the MMP2 and MMP9 expression in aortic aneurysm." (PMID 28683125, 2017). "Indeed, our results also showed UCP-2 knockout up-regulated the MMP2 and MMP9 expression in aortic aneurysm." (PMID 28683125, 2017).
Arrhythmia (2 papers, 2023 to 2024). Any cardiac rhythm other than the normal sinus rhythm. "UCP2 overexpression markedly inhibits mitochondrial Ca2+ uptake, and UCP2 knockout mice were shown to have a higher susceptibility to arrhythmias with decreased APD after ICa-L activation and disturbed Ca2+ homeostasis." (PMID 36899814, 2023). "UCP2 and UCP3 also belong to a superfamily of mitochondrial ion transporters and have been reported in Ca2+ regulation through MCU-related channel mCa1 and arrhythmia induction." (PMID 36899814, 2023). "Among the four genes, UCP2, UCP3, and CPT2 played a crucial role in fatty acid oxidation, it has proven that the downregulation of UCP2 and UCP3 impaired myocardial fatty acid oxidation and elevates the production of reactive oxygen species (ROS), subsequently increasing the incidence of arrhythmia." (PMID 38283583, 2024).
Autoimmunity (2 papers, 2014 to 2025). The occurrence of an immune reaction against the organism's own cells or tissues. "Our results establish a critical link between CTLA4 endocytosis and UCP2-mediated metabolic shift in Tregs and identified UCP2 as a potential therapeutic target for preventing RA autoimmunity." (PMID 41068616, 2025). "Specific mechanisms of UCP2 action in this context may also include regulatory effects on immune cell migration and the production of cytokines and nitric oxide, as previously demonstrated in models of infection, inflammation and autoimmunity." (PMID 24721982, 2014).
Cachexia (2 papers, 2014 to 2023). Severe weight loss, wasting of muscle, loss of appetite, and general debility related to a chronic disease. "The upregulation of UCP-2 and UCP-3 was found to contribute to skeletal muscle loss during cancer cachexia, although some studies indicated that the upregulation of UCPs does not have any direct effect on skeletal muscle loss." (PMID 36900198, 2023). "Up-regulation of genes involved in mitochondrial fat oxidation such as peroxisome proliferator-activated receptor-gamma coactivator 1 alpha (PGC-1α), and uncoupling protein 2 (UCP-2) have been demonstrated in animal models of cancer cachexia." (PMID 25415607, 2014).
chronic pancreatitis (2 papers, 2024 to 2025). A chronic inflammatory process causing damage and fibrosis of the pancreatic parenchyma. "The role of UCP2 in acinar cell injury and macrophage regulation during AP remains unclear, and studies on UCP2 in chronic pancreatitis (CP) are limited." (PMID 39707176, 2024).
congenital hyperinsulinism (2 papers, 2008 to 2023). "However, a possible pathogenic role for UCP2 protein in the development of human congenital hyperinsulinism or of any human disease has not yet been investigated." (PMID 19065272, 2008).
diabetic neuropathy (2 papers, 2006 to 2008). A chronic, pathological complication associated with diabetes mellitus, where nerve damages are incurred due to diabetic microvascular injury involving small blood vessels that supply these nerves, resulting in peripheral and/or autonomic nerve dysfunction. "Interestingly, the same UCP2 -866G/A polymorphism and a -55C/T polymorphism in UCP3 are both associated with significantly reduced prevalence of diabetic neuropathy in type-1 diabetics." (PMID 16968550, 2006).
energy metabolism disorders (2 papers, 2020 to 2021). "Previous studies have suggested that mitochondrial UCP2 is able to slow the process of oxidative phosphorylation, inhibit ATP production, cause cell energy metabolism disorders, and induce apoptosis." (PMID 33013386, 2020). "Previous studies indicated that the upregulation of UCP2 could slow the process of oxidative phosphorylation and inhibit ATP production, thereby causing energy metabolism disorders in cells." (PMID 34960036, 2021).
Hearing impairment (2 papers, 2014 to 2022). A decreased magnitude of the sensory perception of sound. "The UCP1 A3826G polymorphism did not exhibit any significant association with ARHI; however, the UCP2 Ala55Val polymorphism did show a significant association with hearing impairment under the dominant, recessive, and additive models (P < 0.05)." (PMID 25140308, 2014). "Data were analyzed to assess the effects of UCP1 A-3826G and UCP2 Ala55Val polymorphisms on hearing impairment." (PMID 25140308, 2014).
Hepatic failure (2 papers, 2010 to 2025). "The protective action of UCP2 strongly suggests a mitochondrial role in the oxidative damage observed in these models of hepatic failure." (PMID 40991132, 2025).
hyperlipidemia (2 papers, 2019 to 2025). "While smoking, alcohol consumption, and hyperlipidemia are primary risk factors for CP, the critical role of UCP2 in its pathogenesis should not be overlooked, especially given its impact on metabolism and macrophage function." (PMID 40874461, 2025).
hypertriglyceridemia (2 papers, 2016 to 2020). A laboratory test result indicating elevated triglyceride concentration in the blood. "We speculate that there are different temporal effects of WBV (e.g. sympathetic activity) and sustained for others (e.g. increased hepatic UCP2 expression and mitochondrial oxidation, reversed hepatic hypertriglyceridemia)." (PMID 26886917, 2016).
idiopathic pulmonary fibrosis (2 papers, 2022 to 2023). Idiopathic pulmonary fibrosis (IPF) is a nonneoplastic pulmonary disease that is characterized by the formation of scar tissue within the lungs in the absence of any known cause. "High constitutive levels of uncoupling protein‐2 (UCP2) are observed with aging and in the age‐related fibrotic disease, idiopathic pulmonary fibrosis (IPF)." (PMID 35934931, 2022). "In an aging murine model of lung fibrosis, the in vivo silencing of UCP2 induces fibrosis regression." (PMID 35934931, 2022).
Impaired glucose tolerance (2 papers, 2009 to 2020). An abnormal resistance to glucose, i.e., a reduction in the ability to maintain glucose levels in the blood stream within normal limits following oral or intravenous administration of glucose. "Data suggest that ERα knockout mice express impaired glucose tolerance and IR, downregulation of peroxisome proliferators-activated receptors (PPAR), PPARα and PPARΔ, and uncoupling protein-2 (UCP2) expression in skeletal muscle as well as elevated inflammatory signaling in liver." (PMID 32029220, 2020).
kidney injury (2 papers, 2020 to 2023). Trauma to the kidney. "All these results suggested that the renoprotective effect of irisin on AKI may be mediated by the upregulation of UCP2 in I/R-induced kidney injury." (PMID 32934963, 2020).
left ventricular hypertrophy (2 papers, 2017 to 2022). Enlargement of the LEFT VENTRICLE of the heart. "Our data indicated that ALDH2 deficiency did notaffect NX-induced left ventricular hypertrophy, but could increase oxidativestress and exacerbate CKD-induced cardiac dysfunction, partly via downregulationof UCP2 and Nrf2/ARE (antioxidant response element) pathways." (PMID 39076225, 2022).
liver fibrosis (2 papers, 2017 to 2024). "A single-nucleotide polymorphism of UCP2 (rs659366) is strongly associated with severe liver fibrosis." (PMID 39033153, 2024). "More importantly, since liver fibrosis is a pivotal stage in ALD, we also put it under investigation and found a stepwise change of both miR-30e and UCP2 levels with the progression from AFL to AH and AHF." (PMID 28969071, 2017).
pancreatic diseases (2 papers, 2024 to 2025). "The regulation of UCP2 in pancreatic diseases encompasses several mechanisms, including gene mutations, transcription factors influencing UCP2 expression in pancreatic diseases, and UCP2-related epigenetic modifications." (PMID 39707176, 2024). "We have built upon these studies to summarize and update our understanding of the role of UCP2 gene polymorphisms in pancreatic diseases in recent years." (PMID 39707176, 2024). "UCP2 is a gene strongly associated with pancreatic diseases." (PMID 40874461, 2025). "Understanding UCP2’s role and mechanisms in pancreatic diseases may pave the way for innovative therapeutic and diagnostic approaches." (PMID 39707176, 2024). "Clarifying UCP2’s role and mechanisms in pancreatic diseases could provide new directions for therapeutic and diagnostic innovation." (PMID 39707176, 2024). "In conclusion, while the theoretical foundation supports the potential application of UCP2 in pancreatic diseases, clinical validation is necessary." (PMID 39707176, 2024). "Collectively, UCP2 plays a crucial role in regulating energy homeostasis, ROS, insulin secretion, and overall metabolism, influencing the progression of pancreatic diseases and β-cell function via pathways including AMPK, Wnt, and NF-κB." (PMID 39707176, 2024). "This review presents a comprehensive analysis of current research on UCP2’s role in pancreatic diseases." (PMID 39707176, 2024). "By studying these polymorphisms and their functional significance, the role of UCP2 in pancreatic diseases can be better understood." (PMID 39707176, 2024). "ncRNAs play a crucial role in the epigenetic regulation of UCP2 and have potential as biomarkers for diagnosing and prognosing pancreatic diseases." (PMID 39707176, 2024). "These intricate regulatory mechanisms precisely control UCP2 gene expression under diverse physiological and pathological conditions, thereby fully elucidating the role of UCP2 in pancreatic diseases." (PMID 39707176, 2024). "Given UCP2’s diverse functionality, broad expression in pancreatic tissue, and the distinct pathophysiological features of pancreatic diseases, this review offers a comprehensive analysis of current findings on UCP2’s involvement in these conditions." (PMID 39707176, 2024). "Investigating UCP2 regulation is essential for understanding its role in pancreatic diseases and underscores its potential as a central therapeutic target." (PMID 39707176, 2024). "We discuss recent insights into UCP2’s complex regulatory mechanisms, propose that UCP2 may serve as a central regulatory factor in pancreatic disease progression, and hypothesize that UCP2 dysfunction could significantly contribute to disease pathogenesis." (PMID 39707176, 2024). "Additionally, the precise mechanisms of UCP2's action in pancreatic diseases remain inadequately understood." (PMID 39707176, 2024). "We discuss recent findings on UCP2’s complex regulatory mechanisms, propose UCP2 as a central regulatory factor in pancreatic disease progression, and hypothesize that UCP2 dysfunction could significantly contribute to disease pathogenesis and interconversion." (PMID 39707176, 2024). "Inevitably, there are challenges for UCP2 as a therapeutic target for pancreatic diseases." (PMID 39707176, 2024). "Overall, UCP2-regulated macrophage phenotypic transformation appears to significantly impact the progression of pancreatic diseases, lending further support to the hypothesis that UCP2 is a central regulatory factor in these conditions." (PMID 39707176, 2024). "Furthermore, ncRNAs are vital regulators of pancreatic diseases, influencing inflammation, fibrosis, insulin secretion, and cell survival.In this section, we summarize the ncRNAs involved in the epigenetic regulation of UCP2." (PMID 39707176, 2024).
pancreatic diseases (continued). "Given UCP2’s diverse functions, widespread expression in pancreatic tissue, and the interconnected pathophysiology of pancreatic diseases, this review examines current findings on UCP2’s regulatory role, proposing that UCP2 dysfunction may play a central role in pancreatic disease pathogenesis." (PMID 39707176, 2024).
pancreatic ductal adenocarcinoma (2 papers, 2023 to 2024). An infiltrating adenocarcinoma that arises from the epithelial cells of the pancreas. "UCP2 was found to function crucially in pancreatic ductal adenocarcinoma (PDAC), and that UCP2 silencing reduces glutaminolysis and nicotinamide adenine dinucleotide phosphate (NADPH) production in P DAC cell lines, ultimately affecting tumor growth." (PMID 37007021, 2023).
progeria (2 papers, 2022 to 2025). "Many genes, such as CCL2 and UCP2, were upregulated in progeria whilst CD27, CD28, and TIGIT were dysregulated in senescent cells." (PMID 40343591, 2025). "At the same time, progeria patients have higher UCP2 levels than healthy children." (PMID 36289702, 2022). "Some genes that are downregulated during aging are upregulated in progeria patients (KRT8, KRT18, UCP2, ADAMTS15, ACTN4P1) while others (ACKR4) are upregulated in nonagenarians but downregulated in children suffering from HGPS." (PMID 36289702, 2022). "We also present here the miRNAs and interactomes for the three genes connecting aging, the aging pathway, and progeria: WNT16 (hsa-mir-181a-5p), UCP2 (hsa-mir-26a-5p and hsa-mir-124-3p), and IGFBP2 (hsa-mir-124-3p, hsa-mir-126-3p, and hsa-mir-27b-3p)." (PMID 36289702, 2022). "Another aging-related gene, UCP2 (Uncoupling Protein 2), is shown as upregulated in progeria compared to healthy children and nonagenarians." (PMID 36289702, 2022). "While UCP2 is upregulated in progeria, it is downregulated in nonagenarians." (PMID 36289702, 2022). "Healthy children and progeria patients express more UCP2 than nonagenarians." (PMID 36289702, 2022). "However, in progeria, the high UCP2 levels do not correlate with patient’s body weight, as low body weight is one of the characteristics of progeria." (PMID 36289702, 2022). "Despite progeria being known as premature aging, only three genes of the aging pathway are differentially expressed in nonagenarians and progeria patients compared to the same group of healthy children: WNT16, UCP2, and IGFBP2." (PMID 36289702, 2022).
prostate adenocarcinoma (2 papers, 2021 to 2022). "In contrast, in prostate adenocarcinoma tissues, UCP2 expression is reduced, while several MAM-stabilizing proteins, including AKAP1, RICTOR, GPR75, and PEMT1, were found to be upregulated." (PMID 33614647, 2021).
pulmonary arterial hypertensive (2 papers, 2017 to 2018). "In fact, Ucp2-/- mice develops spontaneous pulmonary arterial hypertension and vascular remodeling, due to the deficiency of Ucp2 in vascular smooth muscle, which causes mitochondrial membrane hyperpolarization, lowers mitochondrial calcium, and inhibits enzymes such as pyruvate dehydrogenase." (PMID 30116205, 2018). "Interestingly, loss-of-function genetic variant of UCP2 in pulmonary arterial hypertensive patients causes resistance to PDK inhibitors, due to the regulation of PDH (the downstream target of PDK) by UCP2-dependent mitochondrial calcium homeostasis." (PMID 30116205, 2018).
schizophrenia (2 papers, 2012 to 2022). A major psychotic disorder characterized by abnormalities in the perception or expression of reality. "SNPs in and around the UCP2 and UCP4 genes were investigated in subjects with schizophrenia." (PMID 22950050, 2012).
abortion (1 paper, 2025). the ending of pregnancy by removing a fetus or embryo before it can survive outside the uterus. "These insights suggest that oxidative stress-induced senescence plays a critical role in recurrent spontaneous abortion, with UCP2 and GSR as promising biomarkers and therapeutic targets to improve endometrial health and reduce miscarriage risk." (PMID 41387654, 2025).
acute lymphoblastic leukemia (1 paper, 2024). Leukemia with an acute onset, characterized by the presence of lymphoblasts in the bone marrow and the peripheral blood. "In T-cell acute lymphoblastic leukemia (T-ALL) cell line HPB-ALL, glutamine upregulates UCP2, and UCP2 silencing leads to TCA intermediate accumulation in the matrix, reducing OCR and cell proliferation rates." (PMID 39795950, 2024).
age-related hearing loss (1 paper, 2022). "Both the UCP2 and ROS are increased in cochleae in age-related hearing loss (ARHL)." (PMID 36266633, 2022).
alcoholic steatohepatitis (1 paper, 2016). "In increased mRNAs, UCP2 was found to participate in hepatic simple steatosis; CIDEC was identified to promote alcoholic steatohepatitis in mice and humans and Acot2 was located at mitochondria matrix and associated with lipid metabolism." (PMID 27677588, 2016).